TNF (tumor necrosis factor)
Diseases named in the same sentence as TNF in open-access papers (continued):
Sharing a sentence is not in itself a finding about the gene and the disease.
colon carcinoma (continued). "Although TNF-α induces apoptosis in colon cancer cells, it can also induce the proliferation and migration of colon cancer cell lines." (PMID 37185713, 2023). "It inhibits the activation of inflammasomes mediated by NF-κB, TNF-α and mitochondrial autophagy, resulting in reduced secretion of IL-1β and IL-6, thereby delaying the progression of colon cancer and reducing the tumor load." (PMID 37020871, 2023). "HT-29 colon carcinoma cells treated with a combination of TNF-α, cycloheximide, and Z-VAD-FMK were used a positive control." (PMID 35436470, 2022). "The increase of the expression of TLR4 and the increase of the production of CCL2, COX-2, PGE2, and TNF-α compromise the regeneration of the mucosa, with consequent tissue damage that over time can lead to the development of cancer of the colon." (PMID 35204289, 2022). "Then, we used TNFα to stimulate the human colon cancer cells HCT116 and SW480 and used NEC-1 to inhibit the occurrence of necroptosis in the cells." (PMID 36505813, 2022). "IP6 has been shown in studies to enhance Natural Killer cell (NK cell) activity, increase Tumor Necrosis Factor (TNF-α) expression, inhibit proliferation and induce apoptosis of colon cancer cells, which has shown an excellent anti-tumor activity." (PMID 36118769, 2022). "Inhibition of IL-8 by moxifloxacin was observed in colon cancer and IL-1β and TNF-α in leukemia cells." (PMID 35756639, 2022). "Among many pro-inflammatory cytokines, the role of tumor necrosis factor alpha (TNF-α) in colon cancer has been extensively reviewed." (PMID 36429712, 2022). "The present study demonstrates for the first time that SMYD2 specifically regulates TNF-induced apoptosis and necroptosis in colon tumor cells." (PMID 35022391, 2022). "CD59 expression is also induced by two of the most eloquent cytokines—IL-1β and TNF-α—in colon cancer cells." (PMID 36499628, 2022). "Taken together, we identified SMYD2 as an important molecule for colon tumor growth via regulating TNF-induced apoptosis and necroptosis." (PMID 35022391, 2022). "The colorectal cancer cell line (HCT116) was induced by LPS/TNF-α and the inflammation and metastatic mediators (IL-1β, IL-6, IL-17) were quantified in calcitriol and capric acid supplemented colon cancer cells." (PMID 36235161, 2022). "Treadmill running (15–30 min at 15–20 m/min, 3 days/week, 6 weeks) also reduces TNF-α concentration in the plasma and TNF-α gene expression in the colon of mice with azoxymethane (AOM)-induced colon cancer." (PMID 35626116, 2022). "In addition, KEGG analysis showed that the enriched KEGG pathways in patients with low-risk colon cancer compared with the high-risk group were cytokine–cytokine receptor interaction, cell cycle, chemokine signaling pathway, NK cell-mediated cytotoxicity, and TNF signaling pathway." (PMID 35991554, 2022). "The expression of TNF-β and TNF-α and their receptors can induce the activation of NF-κB and NF-κB-related genes, thus regulating the survival, metastasis, etc. of colon tumors." (PMID 36003525, 2022). "HCT-116 (Human Colon Cancer) cell lines were used to estimate the total antioxidant capacity and lipid peroxidation levels and pro-inflammatory markers (human IL-6, IL-1β, TNF-α)." (PMID 35204178, 2022). "The tumor microenvironment is closely related to the occurrence and development of cancer, while TNF is frequently present in the tumor microenvironment as an important inflammatory cytokine that promotes the invasion and metastasis of colon cancer." (PMID 36046463, 2022). "Inhibition of the TNF-a pathway demonstrated a significant protective effect on RILI in a mouse model of colon cancer lung metastasis." (PMID 35360660, 2022). "IFNγ and its signaling induce PD-L1 in TNBC, IFNα upregulates PD-L1 in dendritic cells, and TNFα upregulates PD-L1 in prostate and colon cancer cells." (PMID 35053979, 2022).
colon carcinoma (continued). "Collectively, our data show that SMYD2 is crucial for colon tumor growth and inhibits TNF-induced apoptosis and necroptosis." (PMID 35022391, 2022). "(A) IL‐6 and (B) TNF‐α secretion were analyzed by ELISA in stage II and IV colonic tumor tissue and precancerous tissue." (PMID 33882644, 2021). "Accordingly, high values of CA-19.9, TNF-α, PCT, PTX-3, and CRP were found to pose a high risk for colon cancer." (PMID 33776564, 2021). "PTX-3 is mainly induced by NF-κB and proinflammatory cytokines, such as IL-6 and TNF-α in breast and colon cancer." (PMID 33776564, 2021). "For instance, 5-FU-treated colon cancer cells underwent necroptosis upon caspase inhibition that was mediated by autocrine secretion of TNFα, while autocrine TNFα was only partially required for cisplatin-induced lethality in L929 cells." (PMID 34200309, 2021). "Association between IL‐6/TNF‐α and the expression of LYPD8 in colonic tumor tissue, precancerous tissue and normal tissue at different stages." (PMID 33882644, 2021). "In the current study, the circulating TNF-α levels in breast and colon cancer were significantly higher than in control groups." (PMID 33776564, 2021). "The average number of colonic tumors and the levels of IL-6 and TNF-α in the CC + GL group were significantly lower than those in the CC group." (PMID 33807620, 2021). "JUG was also reported to inhibit TNF‐α and Nuclear Factor-kappa B (NF-κB) production in colonic cancer cells." (PMID 34421890, 2021). "In colon cancer, direct injection of TNF-α into liver metastases has shown to be an effective therapy in preclinical testing and was shown to have acceptable safety in a small phase I trial of colon cancer patients." (PMID 34063789, 2021). "The TNFRSF18 and TNFSF12 genes are related to tumor necrosis factor (TNF), which is a well-known inflammatory biomarker that promotes cytokines in colon cancer." (PMID 33670198, 2021). "Experimental and clinical studies on the role of TNF-α have demonstrated that the TNF-α is a key player in the progression of human breast and colon cancer." (PMID 33776564, 2021). "This study evaluated the inhibitory effect of astragalin on TNF-α-induced in colon cancer HCT116 cells activated." (PMID 33953676, 2021). "The results of recent study have revealed that pro-inflammatory cytokines including IL-6 and TNF-α decreased CYP27B1 expression in colon cancer cells." (PMID 34208589, 2021). "UBD which also contributes to colon cancer progression was observed to be upregulated in the datasets and its expression was predicted to be induced by TNF-α in transformed epithelial cells." (PMID 34946170, 2021). "Immunofluorescence staining showed that Srx depletion notably increased the number of TNFα/CHX-induced γH2Ax foci in colon cancer cells." (PMID 34798428, 2021). "Studies have shown that ginsenoside rh2 upregulates the secretion levels of TNF-α and IL-6 in the serum of colon cancer mice, relieves tumor-related immunosuppression, and prolongs the survival of colon cancer mice." (PMID 33688358, 2021). "The TNF-α levels in colon cancer subjects and controls were 41.56 ± 2.47 pg/ml and 24.29 ± 2.18 pg/ml, correspondingly." (PMID 34096454, 2021). "Paradoxically, improved disease-free survival is observed in stage III colon cancer patients expressing a high level of M1 macrophages, suggesting a synergistic effect through immunogenic death with 5-FU via TNFα/TRAIL." (PMID 34571731, 2021). "An increase in CAFs resulted in an increase in the number of infiltrating macrophages and CD8-positive T cells, consistent with an increase in proinflammatory cytokine levels of IL-1α, IL-1β, IL-6 and tumor necrosis factor (TNF) in colon cancer." (PMID 33572742, 2021).
colon carcinoma (continued). "TNFα was also described to regulate PD-L1 expression trough NF-κB signaling activation in human prostate and colon cancer cells." (PMID 32486375, 2020). "We found that TNF mRNA expression was significantly increased in colon tumor tissues from CRC patients compared to healthy controls (P = 0.0498)." (PMID 32171282, 2020). "HT29 colon cancer cells are widely used to detect necroptosis by co-treatment with TNFα, BV6 (IAP inhibitor) and z-VAD-fmk (caspase inhibitor), and MLKL (mixed lineage kinase domain like pseudokinase) phosphorylation is used as a marker of necroptosis." (PMID 32354117, 2020). "Trichomicin inhibited TNFα-induced NF-kB phosphorylation and induced activation of Stat3-related signaling pathways in a dose-dependent manner in colon cancer cells." (PMID 32317968, 2020). "Conclusively, Trichomicin, a promising new drug candidate with antitumor activity, exerted antitumor effects against colon cancer through inhibition of the IL-6 and TNFα signaling pathways." (PMID 32317968, 2020). "The effects of orally administered probiotics on basic cancer and immune parameters and cytokine concentration (TNF-α, IL-1β, IL-18) in colon tumours were studied." (PMID 32168834, 2020). "Cytokines that promote colon tumor development include the tumor necrosis factor (TNF), interleukin 6 (IL-6), interleukin 1B (IL-1B), and interleukin 8 (IL-8)." (PMID 32983990, 2020). "Based on these findings, we evaluated the antitumor effects of Trichomicin against colon cancer in a colorectal tumor animal model, and evaluated the role IL-6 and TNFα in these effects." (PMID 32317968, 2020). "A previous study showed that TNFα induces the COX2 expression via activation of the NFkB signaling pathway in human colon cancer cells, and activation of P38/MAPK pathway in colonic myofibroblast." (PMID 32986377, 2020). "It has been shown that proinflammatory cytokines, such as interleukin-6 (IL-6) and tumor necrosis alpha (TNF-α), inhibit vitamin D metabolism in colon cancer cells." (PMID 32422882, 2020). "The nuclear translocation of p65 and p50 was significantly increased in TNF-α-activated colon cancer cells while CyCl treatment abrogated the translocation of these subunits to the nucleus." (PMID 32230772, 2020). "C1 (Tumor-Treg) showed 112 DEGs between colon cancer and rectal cancer, such as TNF and CXCR3, which were up-regulated, while CXCR6 and CCR6 were down-regulated in colon cancer in comparison to that of rectal cancer." (PMID 33584715, 2020). "In the present study, we evaluated the efficacy of CyCl on NF-κB signaling in TNF-α treated colon cancer cells." (PMID 32230772, 2020). "We evaluated the anti-inflammatory effect of NED in a disease-relevant cellular context by using TNF-α stimulated HT-29 colon cancer cells in culture, a well-established model for inflammatory process in the gut." (PMID 32650602, 2020). "In our study, Trichomicin reduced the levels of IL-6 and TNFα in colon cancer tumor tissues, which indicated that it had potential as an adjuvant treatment for colon cancer." (PMID 32317968, 2020). "We found that colon cancer tissue in the mouse model as well as LPS-stimulated CT26.WT cells were in an inflammatory state as indicated by increased expression of TNF-α, IL-6 and adhesion molecules." (PMID 32210720, 2020). "To better define the antioxidant effect of CyCl, we examined the ability of CyCl to modulate the expression of antioxidant enzymes and Nrf2 in TNF-α-stimulated colon cancer cells." (PMID 32230772, 2020). "In conclusion, hsa_circ_0079662, as a ceRNA binding with hsa‐mir‐324‐5p, can regulate target gene HOXA9 and induced the mechanism of chemotherapy drug oxaliplatin resistance in CRC through the TNF‐α pathway in human colon cancer." (PMID 32243061, 2020). "RT-qPCR was carried out to investigate the expression of IL1β, IL6 and TNFα in colon cancer cells stimulated with LPS or siHMGB1." (PMID 32514250, 2020).
colon carcinoma (continued). "Targeting this antigen, found in malignant tissues, allowed for TNF delivery in tumors, and favored the efficacy of peptide anticancer vaccine in mouse colon carcinoma." (PMID 31417576, 2019). "NDV-F vectors expressing G-CSF, IL-2, or tumor necrosis factor (TNF) were evaluated in an immunocompetent colon carcinoma model." (PMID 30832256, 2019). "For this purpose, we developed an automated procedure for the co-staining of miR-21, TNF-α mRNA and the cancer cell marker cytokeratin based on analysis of frozen colon cancer tissue samples (n = 4) with evident cancer cell budding." (PMID 30999696, 2019). "Human colon cancer HT-29 cells were treated with these compounds for 2 h, followed by treatment with necroptotic stimuli (TNFα, Smac mimetic, and z-VAD) that are known to activate TNF-mediated necroptosis." (PMID 31235688, 2019). "Luteolin has been also shown to sensitize colon cancer cells to apoptosis induced by TNF, through the suppression of NF-kappaB." (PMID 31159225, 2019). "In conclusion, we report that miR-21 and TNF-α mRNA both are expressed at the invasive front of colon cancers and are co-localized in a subset of budding cancer cells and cells located at branching points and in clusters of cancer cells." (PMID 30999696, 2019). "This study was undertaken to explore expression of miR-21 and TNF-α mRNA at the invasive front of colon cancers to elucidate interplay between miR-21 and TNF-α." (PMID 30999696, 2019). "In line with our finding, a previous in-vitro study using human colon tumor cells showed that the DAPK/LIMK/p-Cofilin complex participates in TNF-induced apoptosis." (PMID 30870492, 2019). "This study was undertaken to address if in situ localization analyses can help to clarify interplay between miR-21 and the pro-inflammatory cytokine TNF-α during colon cancer progression." (PMID 30999696, 2019). "More recently, in a murine colon cancer model, concurrent treatment with anti-TNFα and combined anti-CTLA-4 and anti-PD-1 improved survival when compared with double checkpoint inhibition treatment alone." (PMID 31439050, 2019). "The phosphorylation of IKK was maximally increased 5 min after TNF-α stimulation in the colon cancer cell line HT-29." (PMID 31484999, 2019). "Apparently, in many inflammatory diseases as well as in colon cancer and lung cancer, the IL-6 trans-signaling pathway plays a dominant role as compared to the TNFα signaling pathway." (PMID 31694340, 2019). "In human eosinophils, the induction of apoptosis in colon cancer cells was shown to be mediated by granzyme-A and TNF-α." (PMID 31717819, 2019). "Ellagic acid was shown to reduce the expression of NF-κB, COX-2, iNOS, TNF-α, and IL-6 in 1, 2-dimethylhydrazine-induced colon cancer." (PMID 30971953, 2019). "Exploration of the expression of inflammatory markers in colon cancers revealed tumor necrosis factor alpha (TNF-α) mRNA expression at the invasive front of colon cancers." (PMID 30999696, 2019). "In the first experiment, we investigated the role of AP on gene expression in TNFα-treated and untreated cells of the human colon carcinoma cell line Caco-2." (PMID 30442133, 2018). "A previous study deemed TNF-α as a pivotal regulator in colon cancer progression and proved that interdicting TNF-α in a mice model can lessen colonitis-related carcinoma of the colon." (PMID 30386232, 2018). "The effects of TNF-α on regulation of TROP-2 expression in colon cancer indicated that low concentrations increase TROP-2 protein expression, while higher concentrations of TNF-α have a decreasing influence." (PMID 29989029, 2018). "In both CT26 and MC38 models of colon cancer, addition of bone marrow-derived macrophages to tumors led to increased IL-1β, IL-6, and TNF-α at significant levels with the exception of IL-1β in MC38 tumors." (PMID 30298062, 2018).
colon carcinoma (continued). "F. nucleatum attaches to cancer tissues through the interaction of Fusobacterium lectin Fap2 with tumour-specific surface Gal-Gal NAc, and this interaction leads to MUC2 and TNFα expression in the colon cancer cells." (PMID 29317709, 2018). "The present investigation deals with the anti-cancer activity of zerumbone against HCT116 cells (colon cancer cell line) and its subsequent role in TNF-alpha inhibition in cancer cell proliferation." (PMID 29511228, 2018). "A previous study on colon carcinoma spheroids derived from LIM1863 cells suggested that TNF-a stimulates TGF-β1-induced EMT and chemotactic migration." (PMID 28550311, 2017). "In conclusion, we demonstrated that co-culture of C2C12 myotubes with CT26 colon carcinoma cells increased TNF-α and myostatin concentrations in the culture medium." (PMID 29069832, 2017). "Our results show that tumor necrosis factor (TNF)-α-preactivated-hMSCs significantly promote the progression of colon cancer cells by enhancing cell proliferation, epithelial–mesenchymal transition, migration, and invasion." (PMID 28542126, 2017). "In support of these previous findings, the present study clearly shows that TNF-α-treated BM-MSCs promote colon cancer cell EMT and progression." (PMID 28542126, 2017). "Collectively, these results suggest that CCL5/CCR1/β-catenin/Slug pathway is responsible for the tumor-promoting effects of TNF-α-activated hMSCs on the development of colon cancer." (PMID 28542126, 2017). "TNF-α can induce the apoptosis while with potentially induction of invasion and metastasis of colon cancer cells." (PMID 29202800, 2017). "Our results show that TNF-α-pretreated hMSCs promote colon cancer EMT and metastasis via β-catenin/Slug pathway." (PMID 28542126, 2017). "We examined the sensitivity of eight colon cancer cell lines to TNFα-induced necroptosis in response to combined treatment with three well-known necroptosis inducers: TNFα, Smac mimetic and z-VAD." (PMID 28981102, 2017). "Here, AFM was carried out to investigate the morphology and mechanical properties of EMT in HCT116 human colon cancer cells, which evaluated the effect of TNFα on cancer cells." (PMID 29109804, 2017). "Increased expression of Par-4 in renal carcinomas renders them sensitive to TNF-α mediated cytotoxicity and 5-fluorouracil-induced apoptosis in human colon cancer cell line, HT29." (PMID 29278364, 2017). "In HT-29 colon cancer cells, butyrate prevented TNFα-mediated activation of COX-2 transcription and protein synthesis similar to trichostatin-A, a synthetic high-affinity HDAC inhibitor." (PMID 29259973, 2017). "Treatment of HT-29 human colon carcinoma cells by TNF-α for 24 hours induces the secretion of the proinflammatory cytokine IL-8 in a dose-dependent manner." (PMID 27054921, 2016). "By comparison, TNFα is a crucial mediator of IFNα/BV6-induced cell death in HT-29 colon carcinoma cells, since pharmacological blockage of TNFα rescues cell death by IFNα/BV6." (PMID 26788912, 2016). "Treatment of colon carcinoma HT-29 cells with IL-4 and TNFα led to an increase in fibronectin adhesion in vitro with a corresponding decrease in lung colonizing potential in vivo." (PMID 27556857, 2016). "As an example, IL-32γ enhances TNF-α-induced cell death in cases of colon cancer and inhibits the growth of cancer cells by blocking the NF-κB and STAT3 pathways." (PMID 26824417, 2016). "In short, the cycloartane induced apoptosis in HT-29 colon cancer cells that mimics the TNF-induced apoptosis possibly by binding through TNFR1, which needs further investigation." (PMID 27070314, 2016). "Vice versa, colon cancer cells were able to induce secretion of cytokines (TNFα, IL10, IFNγ) and metastasis-related factors (VEGFC, MMPs) in MSC via activation of Wnt signaling which in turn resulted in activation of Wnt pathways in colon cancer cells." (PMID 27608835, 2016).